UBL4B (ubiquitin like 4B)
Synonyms: FLJ25690
Tractability: No criterion of Open Targets' tractability assessment is met for any kind of drug.
Gene: Protein-coding gene on chromosome 1 (110,112,443 to 110,113,947, forward strand). Ensembl gene ENSG00000186150.
Subcellular location: Cytoplasm
Gene Ontology:
Molecular function: protein binding
Biological process: positive regulation of establishment of protein localization to mitochondrion
Cellular component: cytoplasm
Genetic constraint (gnomAD): Loss-of-function variants: 0 observed, 1 expected, observed/expected ratio (o/e) 0, 90% interval 0 to 1.72. That is too few expected variants to judge how well the gene tolerates losing a copy. Missense variants: 194 observed, 218.32 expected, observed/expected ratio (o/e) 0.89, 90% interval 0.79 to 1. Synonymous variants: 94 observed, 97.18 expected, observed/expected ratio (o/e) 0.97, 90% interval 0.82 to 1.15.
Homologues: Orthologues: chimpanzee UBL4B (97% identical), guinea pig UBL4B (70% identical), mouse Ubl4b (68% identical), rat Ubl4b (67% identical), dog UBL4B (57% identical). Paralogues in human: UBL4A (39% identical), ZFAND4 (24% identical), ANKUB1 (21% identical), ISG15 (18% identical), RPS27A (16% identical), UBC (16% identical), UBA52 (14% identical), UBD (13% identical), NEDD8 (11% identical), UBB (2% identical).
Diseases named in the same sentence as UBL4B in open-access papers:
UBL4B is named in the same sentence as 1 disease in open-access papers, as found by Europe PMC text mining. Sharing a sentence is not in itself a finding about the gene and the disease. The quoted sentences say what the papers report.
ovarian carcinoma (1 paper, 2009). A malignant neoplasm originating from the surface ovarian epithelium. "We tested for the expression of five of the known retrogenes, UTP14C, PGK2, RPL10L, RPL39L and UBL4B in normal human ovary and ovarian cancers." (PMID 19333399, 2009).